CCL7 (C-C motif chemokine ligand 7)
Diseases named in the same sentence as CCL7 in open-access papers (continued):
Sharing a sentence is not in itself a finding about the gene and the disease.
malignant glioma (1 paper, 2020). A grade III or grade IV glioma arising from the central nervous system. "Furthermore, both MARCO and CCL7 promoted the upregulation of tafazzin (TAZ), which has been suggested as a key transcriptional coactivator regulating mesenchymal trans-differentiation in malignant gliomas." (PMID 32847614, 2020).
mastocytoma (1 paper, 2023). A localized tumor composed of sheets of mast cells without atypia. "It was reported that T cell-dependent anti-tumor immunity was activated in mice transplanted with the mastocytoma cell line (P815) transfected with a gene encoding CCL7." (PMID 37046033, 2023).
meningitis (1 paper, 2021). A disorder characterized by acute inflammation of the meninges of the brain and/or spinal cord. "However, only CCL7 levels were shown to be higher in TBE than in non-TBE meningitis." (PMID 34638953, 2021).
mesothelioma (1 paper, 2024). A usually malignant and aggressive neoplasm of the mesothelium which is often associated with exposure to asbestos. "Interestingly, chemokines involved in monocyte/macrophage recruitment and mobilization such as CCL2, CCL3, CCL4, and CCL7 were downregulated in the mesothelioma cell line compared to two other tested cell lines." (PMID 39768223, 2024).
metastatic tumors (1 paper, 2016). "Examination of primary and metastatic tumors by H&E staining revealed that liver and lung metastatic nodules were developed in the CCL7 overexpressing HCT116 cells-injected group but not in mice injected with GFP overexpressing HCT116 cells (data not shown)." (PMID 27167205, 2016).
mucositis (1 paper, 2017). Mucositis is inflammation and damage of the mucous membranes lining the mouth and other parts of the gastrointestinal (GI) tract. "In contrast to our findings on inflammatory markers, our study suggests that local production of immune-modulating chemokines CCL2, CCL7 and KC, coupled with the increase in macrophages and neutrophils within the lamina propria, plays a key role in Doxo-induced mucositis." (PMID 28257503, 2017).
Myocardial fibrosis (1 paper, 2025). "Moreover, activated B cells can recruit inflammatory monocytes Ly6C+ to the myocardium in a Chemokine (C-C motif) ligand 7 (CCL7)-dependent manner, leading to sustained inflammatory progression and myocardial fibrosis." (PMID 40881586, 2025).
parasitemia (1 paper, 2013). "We observed a huge upregulation of CCL2/CCL7 serum levels and an increase in Ccl2/Ccl7 transcription in the BM at peak parasitemia." (PMID 23762028, 2013).
polyp (1 paper, 2021). A usually exophytic mass attached to the underlying tissue by a broad base or a thin stalk. "The CCL2, CCL7, and CCL8 expression seemed to depend on the polyp location, as the lowest expression ratios were observed for the rectal polyps." (PMID 34884259, 2021). "The fold change in CCL2, CCL7, and CCL8 expression was significantly affected by the polyp size." (PMID 34884259, 2021). "The polyp type had a significant impact on the fold change in CCL2, CCL7, and CCL8 expression." (PMID 34884259, 2021). "There were no polyp samples negative for MCP-3/CCL7 in the tested cohort." (PMID 34884259, 2021). "Detailed analysis of the gene expression patterns in the normal mucosa and polyps showed that the CCL2, CCL7, and CCL8 expression in the normal tissue was comparable and not affected by the polyp type, contrary to gene expression in the polyps." (PMID 34884259, 2021). "The polyp expression of CCL2 and CCL8 (but not CCL7) was the lowest in the adenocarcinomas." (PMID 34884259, 2021).
postmenopausal osteoporosis (1 paper, 2023). Metabolic disorder associated with fractures of the femoral neck, vertebrae, and distal forearm. "Currently, CCL7 is being studied as a potential target for postmenopausal osteoporosis." (PMID 37853468, 2023).
prediabetes (1 paper, 2019). "Comparative analysis confirmed that higher levels of IL-33 were associated with significantly lower CCL7 in individuals with normoglycemia (P = 0.02; median 16.7, n = 10 vs. median 118.8, n = 9) but not in those with prediabetes or T2D." (PMID 31073344, 2019). "However, IL-33 was inversely correlated with CCL7 in individuals with normoglycemia (r = −0.5; P = 0.02; n = 19) but not in those with prediabetes or T2D." (PMID 31073344, 2019).
prostate tumors (1 paper, 2024). "Compared to primary prostate tumors, CCR3 exhibits high expression in bone and visceral metastases, potentially exerting its effects via the CCR3/CCL7 axis." (PMID 38511143, 2024).
Pruritus (1 paper, 2023). Pruritus is an itch or a sensation that makes a person want to scratch. "It was shown that the expression of genes encoding inflammatory mediators such as CCL4, CCL7, CCL8, CCL20, interleukin-19 (IL-19), IL-20, IL-26, IL-36A, IL-36G, and TNF-α) was unique to psoriatic skin with pruritus." (PMID 37834183, 2023).
pulmonary emphysema (1 paper, 2024). A subcategory of chronic obstructive pulmonary disease (COPD). "The central role of CCL2 and CCL7, and thus MoAM, in lung inflammation and pathology is corroborated by a strongly impaired recruitment of monocytes into the lung and protection from pulmonary emphysema upon inhibition of the CCR2/CCL2 axis." (PMID 38348034, 2024).
rectal polyps (1 paper, 2021). "The rectal polyps downregulated CCL2 and CCL7 by 3.1-fold and CCL8 by 5.3-fold, while gene downregulation in the colonic polyps was absent or less substantial." (PMID 34884259, 2021).
renovascular hypertension (1 paper, 2021). High blood pressure secondary to renal artery stenosis. "A number of chemokines known to attract mononuclear cells were induced by renovascular hypertension and even more increased in the malignant form of the disease, notably CCL2 and CCL7." (PMID 34528115, 2021).
retinal degeneration (1 paper, 2016). Degeneration of the retina. "Several cytokines and chemokines including MIP-1α (CCL3), MIP-1β (CCL4), MCP-1 (CCL2), MCP-3 (CCL7), TNF-α, IL-1β and IL-6 have been implicated in photoreceptor-microglial crosstalk and retinal degeneration." (PMID 27814376, 2016).
skin inflammation (1 paper, 2017). "To test the importance of several of these molecules in TWEAK-mediated skin inflammation, we blocked CCL2, CCL5 and CCL7 together, by injecting neutralizing antibodies at the time of rTWEAK injection." (PMID 28530223, 2017).
skin inflammatory disorders (1 paper, 2015). "Assessment of Ccl7, Il18, and Il1b expression is most indicative of distinguishing skin rejection from skin inflammatory disorders." (PMID 25756043, 2015).
systemic candidiasis (1 paper, 2012). "In summary, these data establish CCL2/CCL7 as IFN-I-dependent chemokine signals driving the host response during systemic candidiasis." (PMID 22911155, 2012).
tongue cancer (1 paper, 2020). A malignant neoplasm affecting the tongue. "In line with our data, CXCL6 and CCL7 were previously found to be upregulated in tongue cancer cell-induced LECs, suggesting that these factors represent a common mechanism of lymphatics-induced tumor cell progression." (PMID 31963450, 2020).
toxoplasmosis (1 paper, 2024). A parasitic disease contracted by the ingestion or fetal transmission of toxoplasma gondii. "So, it is likely that the upregulated inflammatory genes, such as Ccl5, Ccl3, Ccl7, Ccr5, and Cxcr3, could be the key factors that cause mouse reproductive organ damage, and then contribute to the tragic pregnancy outcomes of toxoplasmosis." (PMID 39006750, 2024).
tubular adenoma (1 paper, 2021). A usually polypoid neoplasm arising from the glandular epithelium. "CCL7 expression in the tubular adenomas was comparable to normal tissue but downregulated in the tubulo-villous and villous adenomas by 2.0- and 5.3-fold, respectively." (PMID 34884259, 2021).
viral meningitis (1 paper, 2019). Inflammation of the membranes surrounding the brain and spinal cord due to a viral infection. "The chemokines CCL3, CCL7, CCL8, and CXCL9 were all significantly elevated in patients with LNB and bacterial and viral meningitis." (PMID 31727097, 2019).
tumor (267 papers, 2007 to 2026). "Cluster 1 contained genes significantly upregulated in AMPKα1/α2–deficient tumor-infiltrating Treg cells and included genes encoding chemokines (Ccl2, Ccl7, Ccl8), modulators of lipid metabolism (Cd36, Pparg, Lpl, Abca1), and glycolytic enzymes (Hk2, Hk3)." (PMID 40100289, 2025). "Conversely, exogenous CCL7 effectively reversed the tumor-suppressive effects of ZBP1-deficient CAFs, restoring malignant phenotypes, i.e., invasion, migration, and proliferation." (PMID 41430036, 2025). "ZBP1 deficiency reduces CCL7 expression in CAFs, diminishing their ability to promote tumor cell proliferation, migration, and invasion via the CCL7/CCR1 axis." (PMID 41430036, 2025). "The overexpression of Ccl7 in cancer is thought to promote the recruitment of tumor-associated macrophages and other immune cells that create a pro-tumorigenic microenvironment." (PMID 39902039, 2024). "In these malignancies, Ccl7 has been associated with tumor progression, metastasis, and poor prognosis." (PMID 39902039, 2024). "In particular, cancer-associated fibroblasts in HCC tumor tissue can secrete CCL7 to promote HCC metastasis." (PMID 38914803, 2024). "Abnormal CCL7 level in tumor microenvironment is associated with tumorigenesis and promotes tumor invasion and metastasis." (PMID 37161570, 2023). "MDSCs navigate the tumor microenvironment through chemokine receptors 2 (CCR2); GBM tumors express two CCR2 ligands, CCL2 and CCL7, which cause the tumor to signal the infiltration of CCR2+ cells." (PMID 37275361, 2023). "In these experiments, we orthotopically transplanted PDGFB-driven primary mGBM tumor cells into the brains of wild-type (WT) mice and mice deficient in Ccl7 or Ccl8/12 expression, a scheme similar to we have shown previously for Ccl230." (PMID 37012245, 2023). "These genes encode for chemokines (CCL2/MCP-1; CX3CL1/Fractalkine; CCL7/ MCP-3) that modulate the immune response but have also frequently been found to be enriched in the tumor microenvironment." (PMID 35661927, 2022). "More specifically, the activation of NF-kB in tumor cells enhances the expression of several genes (including Ccl7, Cxcl1, Ccl5, Slc39a10, Lcn2, Zc3h12a, and Enpp2) that are implicated in tumor migration, angiogenesis, and formation of pre-metastatic niches." (PMID 33567747, 2021). "Gene expression analysis of PIP-expressing 4T1 cells (4T1-PIP) revealed that genes associated with tumor metastasis such as CCL7, MMP3 and MMP13, were significantly upregulated in 4T1-PIP cells when compared to the empty vector control (4T1-EV) cells." (PMID 33777801, 2021). "Regarding CRC, MCP-2/CCL8 derived from cancer-associated fibroblasts have been shown to stimulate the proliferation of cancer cells, while MCP-2/CCL8 and MCP-3/CCL7 derived from tumor-associated macrophages attract anti-tumor CD4+ and CD8+ T cells." (PMID 34884259, 2021). "Some cancer cells, including stomach, colon, prostate, and renal cells, show an abnormal increase in CCL7 expression levels, which is associated with tumor progression." (PMID 34206004, 2021). "We found that the infiltrated cDC1, CD4+, and CD8+ T cells in the tumor-burdened lungs were significantly decreased by CCL7 deficiency." (PMID 33257678, 2020). "Collectively, these data suggest that CCL7 deficiency impairs T cell expansion and accumulation in bronchial dLNs and tumor-burdened lungs of KP mouse model." (PMID 33257678, 2020). "Here, we show that high expression of CCL7 in NSCLC tumor biopsies is positively associated with the OS of NSCLC patients." (PMID 33257678, 2020). "Since CCL7 receptors are barely expressed on CD8+ T cells, we reasoned that the decreased CD8+ T cells in LILs were a result of CCL7 deficiency-caused insufficient cDC1 infiltration in the tumor-burdened lung of KP7 mice." (PMID 33257678, 2020).
tumor (continued). "One of them showed that CCL7 gene transfer to mastocytoma cells caused reduced tumorigenicity, enhanced neutrophil recruitment to the tumor, and dendritic cell infiltration in peritumoral tissue." (PMID 30764543, 2019). "CCL7 upregulation has been associated with many inflammatory settings including infection, cardiovascular disease, and the tumor microenvironment." (PMID 30671055, 2018). "Similarly, elevated levels of CCL7 in the tumor microenvironment have been linked to the advancement and spread of different cancers." (PMID 40918470, 2025). "We used RT-qPCR to validate the differential expression of the five genes most strongly linked to inflammation and tumor immune responses: chemokine Ccl7, cytokine Csf2/GM-CSF, cytokine receptors Il4r and Il18r1, and inhibitor of antitumor immunity through antigen presentation Lilrb3." (PMID 36980301, 2023). "The cellular composition of the TME, the RNA gene expression profiling of T cells, aberrant chemokine and cytokine expression (i.e., CCL7, IL-33), and mutational tumor burden appear to play an important role in determining the efficacy of check point inhibitors-based immunotherapies." (PMID 37041172, 2023). "Moreover, Ccl7 expression is associated with the recruitment of tumor-associated macrophages (TAMs)." (PMID 32659965, 2020). "CCL7 is associated with recruiting inflammatory cells of monocytes, macrophages, and myeloid-derived suppressor cells, which promote the development of type 2 macrophages that inhibit antitumor immune response, thereby allowing tumor progression." (PMID 33175885, 2020). "Actually, the numbers of CD8+ T cells in the bronchial dLNs were significantly decreased by CCL7 deficiency, which might be due to impaired infiltration of cDC1 in the tumor-burdened lungs of KP7 mice." (PMID 33257678, 2020). "Interestingly, several other research groups showed that CCL7 expression can be associated with enhanced invasiveness and tumor metastasis in other types of cancer." (PMID 30764543, 2019). "High CCL7 expression evokes the recruitment of tumor-associated macrophages (TAMs) that express CCR2 on the surface, resulting in the persistence of increased vascular permeability; therefore, tumor cells can cross the blood–brain barrier and move toward brain tissues." (PMID 29915688, 2018). "Furthermore, CCL7 is more abundant in metastatic tumor site than in the primary site, and is associated with macrophage infiltration in tumor." (PMID 25193015, 2014). "CCL2 and CCL7 encode monocyte chemotactic proteins 1 and 3, respectively, known to be strong recruiters of myeloid-derived cells, including monocytes, macrophages, dendritic cells, myeloid-derived suppressor cells, and lymphocytes, regulating tumor microenvironment." (PMID 37334114, 2023). "CCL2 and CCL7 may also cause infiltration of the tumor by TIL, which has an anti-cancer effect." (PMID 33182504, 2020). "Ccl7 attracts monocytes and is associated with the recruitment of tumour-associated macrophages, which enhance tumour malignancy by stimulating tumour angiogenesis, tumour cell invasion, migration, and intravasation, and by suppressing anti-tumour immune responses." (PMID 29138417, 2017). "Specifically, lactate enhances the production of C-C motif chemokine ligand 2 (CCL2) and C-C motif chemokine ligand 7 (CCL7) by tumor cells in CRC, thereby driving the recruitment of CCR2+ polymorphonuclear MDSCs (PMN-MDSCs)." (PMID 41152975, 2025). "Exogenous CCL7 supplementation partially restores tumor growth in Zbp1−/− mice, indicating that ZBP1 bridges CAF–tumor cell communication through the CCL7–CCR1 axis." (PMID 41430036, 2025). "Immunohistochemical co-staining confirmed the systemic downregulation of CCL7 expression in the tumor parenchymal and stromal regions of Zbp1−/− mice." (PMID 41430036, 2025).
tumor (continued). "The current study extends this paradigm by revealing that in OSCC, ZBP1 indirectly activates the CCR1 pathway in tumor cells by regulating CCL7 expression in CAFs, enhancing their proliferation, migration, and invasion." (PMID 41430036, 2025). "In contrast, tumor-derived NOX4-produced hydrogen peroxide induces M2 polarization through HIF-1α stabilization, creating chemokine gradients (CCL7/IL-8) that recruit CCR1+ immunosuppressive macrophages to support tumor progression." (PMID 40733095, 2025). "This study highlights ZBP1 as crucial for OSCC progression by regulating CCL7 expression in CAFs to activate CCR1 signaling in tumor cells." (PMID 41430036, 2025). "Secreted by monocytes, fibroblasts, platelets, and tumor cells, CCL7 binds to its cognate receptors to regulate immune cell chemotaxis, inflammatory responses, and tumor progression." (PMID 41430036, 2025). "BX471 treatment significantly reduced tumor volume in WT mice, whereas recombinant CCL7 supplementation markedly increased tumors in Zbp1−/− mice." (PMID 41430036, 2025). "Chemokine (C‐C motif) ligand 7 (CCL7), known as monocyte chemotactic protein‐3 (MCP‐3), is a chemokine widely expressed in fibroblasts, monocytes, and tumor cells." (PMID 40062588, 2025). "Several investigations have reported a strong association between CCL7, CCL13, CXCL5, and CCR9 and tumorigenesis as well as tumor development." (PMID 41465903, 2025). "CCL7 boosts tumor invasiveness and aids in immune evasion by attracting a variety of immune cells, particularly macrophages." (PMID 40918470, 2025). "ZBP1 orchestrates CAF-derived CCL7 secretion to activate the CCR1 receptor on tumor cells, enhancing their proliferative, migratory, and invasive capacities." (PMID 41430036, 2025). "In parallel, tumor-derived TIMP1 stimulates Schwann-cell proliferation and secretion of CCL7, which in turn enhances tumor cell migration and PNI." (PMID 41394398, 2025). "One recent study pointed out that LDHA upregulated C-C motif chemokine ligand 2 (CCL2) and CCL7 through the ERK-YAP-STAT3 signaling axis to recruit macrophages into the tumor microenvironment." (PMID 40093910, 2025). "They identified loss of Plaur, Mif and Serpine 1 to be responsible for a growth disadvantage of murine ID8 OvCa cells in vivo, whereas Ccl3, Calr and Ccl7 knockout (KO) tumor cells were substantially enriched and formed distinct lesions within the tumors." (PMID 39837825, 2025). "In CRC, HCAR1 signaling promotes the secretion of chemokines CCL2 and CCL7 by tumor cells, which in turn recruit CCR2+ PMN-MDSCs." (PMID 41152975, 2025). "An enzyme-linked immunosorbent assay (ELISA) further demonstrated substantially reduced CCL7 secretion in tumor tissue homogenates." (PMID 41430036, 2025). "IHC staining of the tumor tissues demonstrated that the positive rate of VEGF in the tumor tissues was greatly increased in the CCL7‐treated group compared with the control group." (PMID 40062588, 2025). "Although high CCL7 expression in colorectal, breast, and uterine cancer is known to promote metastasis and suppress tumor immunity, the expression of CCL7 in NSCLC has been shown to be anti-tumorigenic." (PMID 39114657, 2024). "It was recently shown that CCL7 recruits conventional DCs to promote anti-tumor immunity in non-small cell lung cancer (NSCLC)." (PMID 39090759, 2024). "We found freshly sorted PDGFB tumor cells expressed higher levels of Ccl2, Ccl7, Ccl8, and Ccl12 relative to the same cells maintained in vitro (up to 6 passages) under both GSC and FBS conditions (P < 0.05)." (PMID 37733448, 2023). "Upregulation of CCL7 in lungs retarded tumor development and increased the survival of KP and KL mice." (PMID 37033636, 2023). "A recent study has indicated that YTHDF1 is highly expressed in BRCA tumor tissue, creating a “cold” tumor microenvironment by suppressing the release of pro-inflammatory cytokines Ccl7, Il-17rb, Sell, Cxcl2, and Tnfsf4 in BRCA cells." (PMID 38202722, 2023).